EGFR (epidermal growth factor receptor)
Diseases named in the same sentence as EGFR in open-access papers (continued):
Sharing a sentence is not in itself a finding about the gene and the disease.
lung adenocarcinoma (continued). "The L858R mutation, accounts for approximately 43% of EGFR-mutated lung adenocarcinoma." (PMID 40428391, 2025). "During the 139 cases, 96 lung adenocarcinoma cases had EGFR mutations." (PMID 40182027, 2025). "Another case of lung adenocarcinoma harboring EGFR S720F and L861R mutations has been reported." (PMID 41350121, 2025). "EGFR mutation is one of the most prevalent types of gene mutation in lung adenocarcinoma patients." (PMID 40703348, 2025). "However, substantial differences exist in treatment responses and survival outcomes among patients with stages IIIB–IV EGFR-mutated lung adenocarcinoma." (PMID 41268168, 2025). "Similar to a case reported in the literature with an EGFR mutation, our case underscores the importance of considering pituitary metastasis in the differential diagnosis of middle-aged patients with lung adenocarcinoma, which can mimic miliary TB at presentation." (PMID 40556846, 2025). "Moreover, a higher expression rate of p‐STAT3 protein was observed in EGFR mutated‐type lung adenocarcinoma tissues (P = 0.029)." (PMID 39721017, 2025). "These mice, carried a human-derived mutated EGFR with a normal immune system, were used to investigate whether UC-MSCs promote the occurrence of lung adenocarcinoma." (PMID 40892007, 2025). "Furthermore, studies suggest that EGFR mutations play a pivotal role in the evolution of lung adenocarcinoma, enhancing the tumor’s ability to adapt to existing therapies and leading to diminished therapeutic efficacy and the development of resistance." (PMID 41357203, 2025). "We hypothesize that the EGFR genotype in lung adenocarcinoma is associated with specific imaging phenotypes and metabolic characteristics." (PMID 41263395, 2025). "Therefore, we validated the utility of cPANEL by examining the EGFR mutation detection rate in lung adenocarcinoma cells in pleural fluid." (PMID 40616301, 2025). "In lung adenocarcinoma, the rs1897990 C allele may enhance the activity of the EGFR signalling pathway and promote tumor cell survival and metastasis by upregulating EGF." (PMID 40696566, 2025). "Therefore, in this study, we sought to develop and compare logistic regression and decision tree models based on clinical parameters and CT imaging features to noninvasively predict EGFR mutation subtype status in patients with lung adenocarcinoma." (PMID 41049833, 2025). "This included 2024 patients with lung adenocarcinoma and 449 with EGFR mutations." (PMID 41175446, 2025). "Moreover, an additional study indicated that CP metastasis from primary lung adenocarcinoma carrying the EGFR G719X mutation significantly improved following treatment with EGFR inhibitors." (PMID 39780275, 2025). "In conclusion, our research shows that ginsenoside Rg3 can reduce the EGFR copy number, especially in the critical exons of EGFR-mutated lung adenocarcinoma cells, and decrease the levels of EGFR proteins, thus enhancing the effectiveness of EGFR-TKIs when used in combination." (PMID 40732366, 2025). "This article presents two cases of advanced lung adenocarcinoma successfully treated with furmonertinib, aiming to provide clinical insights for this rare patient population and explore the therapeutic potential of EGFR-TKIs in compound mutations." (PMID 40963567, 2025). "Although the efficacy of EGFR‐tyrosine kinase inhibitors (EGFR‐TKI) for EGFR mutation‐positive lung adenocarcinoma has been demonstrated, their effectiveness for EGFR‐mutated squamous cell carcinoma remains unclear." (PMID 40620186, 2025). "Finally, a study using scRNA-seq to analyze EGFR-mutated early lung adenocarcinoma tissues and paraneoplastic normal lung cells unveiled the heterogeneity among malignant subpopulations." (PMID 40003951, 2025).
lung adenocarcinoma (continued). "We enrolled 421 patients with stage IV lung adenocarcinoma and sensitizing EGFR mutations receiving an EGFR-TKI as their first-line therapy, including first-generation (1st G, gefitinib and erlotinib), second-generation (2nd G, afatinib), and third-generation (3rd G, osimertinib) EGFR TKIs." (PMID 40999598, 2025). "Although prior studies suggest a low K-ras mutation rate in GGO-dominant lung adenocarcinoma and mutual exclusivity between EGFR/ALK and K-ras alterations, future research should expand genetic profiling to assess the impact of multi-gene interactions on CT imaging features." (PMID 41020204, 2025). "Our research indicated that EGFR mutations at exon 21 may result in rhabdomyoid differentiation, which connected the genetic changes with the morphological characteristics of lung adenocarcinoma." (PMID 40182027, 2025). "About 20% of patients with lung adenocarcinoma have EGFR mutations, which are oncogenic drivers." (PMID 40729346, 2025). "Notably, two patients with lung adenocarcinoma harboring the EGFR 19del and T790M mutations acquired the C797S mutation after failing osimertinib treatment and subsequently achieved partial remission with gefitinib." (PMID 40277759, 2025). "EGFR-mutant lung adenocarcinoma is a prime example where co-mutations stratify patient outcomes." (PMID 40723270, 2025). "Additionally, podoplanin-positive CAFs have been implicated in EGFR TKI resistance in EGFR-mutant lung adenocarcinoma, as evidenced by in vitro studies showing that cancer cells co-cultured with these CAFs exhibit increased resistance." (PMID 40002883, 2025). "Although molecular profiling was not the primary endpoint of this study, it is worth noting that our center was already performing EGFR mutational testing in early-stage resected lung adenocarcinoma during the study period (2016–2020), anticipating current precision medicine approaches." (PMID 41030941, 2025). "Asian patients with stage IB lung adenocarcinoma are predominantly Epidermal growth factor receptor (EGFR) mutated and exhibit better prognosis, whereas Caucasian populations show higher prevalence of Kirsten rat sarcoma viral oncogene homolog (K-ras) mutations." (PMID 40624509, 2025). "Furthermore, our findings indicate that lung adenocarcinoma patients with a history of alcohol consumption have a lower rate of EGFR mutations and a higher rate of KRAS mutations." (PMID 39926430, 2025). "The prominent expression of CCR2 in specific clinicopathologic/molecular subgroups of lung adenocarcinomas harboring oncogenic mutations in EGFR and KRAS, as well as in CRCs with microsatellite instability–high status further support the potential for refined patient selection." (PMID 39918395, 2025). "EGFR is the second most common driver mutation in lung adenocarcinoma (LUAD)." (PMID 40299444, 2025). "Notably, emergence of the FGFR3::TACC3 fusion as a resistance mechanism in TKI-treated EGFR-mutated lung adenocarcinoma was associated with a tendency towards SCC-like transdifferentiation." (PMID 39387893, 2025). "Additionally, the epidermal growth factor receptor (EGFR) mutation rate in Taiwanese lung adenocarcinoma patients is remarkably high, at 50–60%, compared to the 10–20% observed in Western populations." (PMID 40361443, 2025). "In addition, we found that the EGFR mutation occurred more frequently in moderately differentiated lung adenocarcinoma than well differentiated adenocarcinoma." (PMID 40182027, 2025).
lung adenocarcinoma (continued). "Another randomized, double-blind, placebo-controlled trial involving 354 EGFR mutation-positive advanced lung adenocarcinoma patients showed that the combination of herbal medicine and EGFR-TKI treatment significantly improved median progression-free survival (PFS) compared to EGFR-TKI monotherapy." (PMID 40109719, 2025). "Along similar lines, a prospective phase 2 randomized clinical trial was conducted to evaluate and compare the efficacy of a combination of metformin and EGFR-TKIs with EGFR-TKIs alone in stage IIIB-IV lung adenocarcinoma patients harboring an activating EGFR mutation." (PMID 40983975, 2025). "DKK1 overexpression in lung adenocarcinoma has been reported to promote tumor growth and, interestingly, has been linked to resistance to anti-EGFR therapy, allowing speculation on a possible role of DKK1 in EGFR downstream activation." (PMID 39795613, 2025). "Furthermore, both univariate and multivariate analyses identified PD-L1 expression ≥1% as a significant prognostic factor for RFS in patients with EGFR-mutated lung adenocarcinoma." (PMID 39281386, 2024). "In summary, ramucirumab may have similar effectiveness as bevacizumab in combination with an EGFR‐TKI as first line therapy for advanced lung adenocarcinoma harboring susceptible EGFR mutation." (PMID 38523603, 2024). "The NEOS study updated the results of osimertinib as neoadjuvant therapy in patients with EGFR-mutated resectable stage II-IIIB lung adenocarcinoma at the 2022 European Society for Medical Oncology (ESMO) Congress, thus, further supporting the advantages of osimertinib over other EGFR-TKIs." (PMID 38414743, 2024). "Furthermore, a multivariate analysis revealed that PD-L1 positivity was an independent significant factor for RFS in EGFR-mutated lung adenocarcinoma (p=0.013)." (PMID 39281386, 2024). "We further investigated whether the PD-L1 expression status has intrinsic implications for postoperative recurrence in patients with surgically resected EGFR-mutated lung adenocarcinoma." (PMID 39281386, 2024). "MPE could offer a reference for the EGFR mutation to inform the EGFR-TKI treatment decision for advanced lung adenocarcinoma patients, even when tissue and plasma were available." (PMID 39596989, 2024). "Among 148 patients with lung adenocarcinoma, 49 cases had EGFR mutations." (PMID 37775991, 2024). "Despite significant advancements in the treatment of EGFR-mutated lung adenocarcinoma, such as targeted therapies for this mutation, its performance and mechanisms in breast metastasis remain unclear." (PMID 39193383, 2024). "Patients with advanced lung adenocarcinoma with an EGFR T790M mutation may benefit from longer progression-free survival and a greater rate of disease control when WMN and oxitinib are combined." (PMID 38957318, 2024). "However, six months later, the lung adenocarcinoma had metastasized to the pleura, pericardium, and diaphragm, alongside the presence of an EGFR mutation." (PMID 39811212, 2024). "Another Pakistani study found EGFR mutations in 29% of primary lung adenocarcinoma patients." (PMID 39429333, 2024). "They observed the lung adenocarcinoma caused by mutation in CTNNB1 may show post‐operative reoccurrence in patients having mutated EGFR." (PMID 39434198, 2024). "Accordingly, we addressed tumor heterogeneity by investigating cells harboring major mutations that are commonly found in lung adenocarcinoma, utilizing H1975 (EGFR L858R and T790M), PF901 (BRAF V600E), PF139 (KRAS G12C), and H838 (triple wild type with no known driver mutation) cell lines." (PMID 39227650, 2024). "Multivariate analysis of EGFR mutation status in patients with lung adenocarcinoma with MPE." (PMID 37775991, 2024). "However, in the three EGFR-mutated lung adenocarcinoma cell lines, TKIs mainly inhibited cell proliferation, arresting cells in the G0/G1 phase of the cell-cycle." (PMID 39001552, 2024).
lung adenocarcinoma (continued). "CT features of lung adenocarcinoma patients have been shown to correlate with EGFR mutations." (PMID 39834943, 2024). "Patients having both diseases (hypopharyngeal cancer and EGFR‐mutated lung adenocarcinoma) concurrently may have a higher possibility of cure by using our suggested drug compounds." (PMID 38783639, 2024). "The pathological report confirmed a pT1aN0 lung adenocarcinoma, PD-L1 <1%, and an EGFR mutation (p." (PMID 40027142, 2024). "The number of brain metastases in patients with EGFR-mutated lung adenocarcinoma could serve as a reflection of the tumor burden within the brain." (PMID 38515096, 2024). "EGFR mutations occur in 10–20% of the lung adenocarcinomas in Western populations." (PMID 38891886, 2024). "This retrospective study enrolled 47 patients diagnosed of stage IV lung adenocarcinoma with exon 19 deletion or L858R point mutation, receiving a first‐line EGFR‐TKI with anti‐VEGF agent, including 34 (72%) and 13 (28%) patients receiving bevacizumab and ramucirumab, respectively." (PMID 38523603, 2024). "Lung adenocarcinoma may harbor both activating and resistance mutations of the EGFR gene, and further, mutations of KRAS and BRAF oncogenes." (PMID 38953007, 2024). "We present two cases of advanced lung adenocarcinoma with two EGFR -mutations at initial diagnosis." (PMID 39555453, 2024). "CEA testing of pleural fluid after CPBR has a high predictive efficacy for EGFR mutation in lung adenocarcinoma patients with MPE, implying pleural fluid extracted for cell block after CPBR may be an ideal specimen for genetic testing." (PMID 37775991, 2024). "The latest research indicates that specific glycosylated MUC21 may be involved in the development of lung adenocarcinoma with EGFR mutations." (PMID 38933439, 2024). "EGFR‐mutated lung adenocarcinoma patients and those with hypopharyngeal cancer: predicated drugs." (PMID 38783639, 2024). "However, it was reported that 18F-FDG PET/CT radiomic features have significant potential in predicting EGFR mutation subtypes in patients with lung adenocarcinoma, achieving a notable AUC of 0.87 for the combined model of predicting EGFR mutation positivity." (PMID 39834943, 2024). "Of note, if multiple lesions share only one hotspot mutation, such as EGFR p.L858R (which occurs in approximately 40% of Asian lung adenocarcinoma patients), the presence of other shared somatic mutations should be cautiously reviewed to determine the clonal relationship between multiple tumors." (PMID 39411141, 2024). "Furthermore, data from lung adenocarcinoma patients has confirmed that high PD-L1 expression on macrophages was correlated with the presence of EGFR mutation, a lower cancer grade, and a shorter cancer-specific overall survival." (PMID 38659003, 2024). "In addition, we also found that carcinoembryonic antigen testing of pleural fluid after closed pleural brushing has a high predictive efficacy for epidermal growth factor receptor mutation in lung adenocarcinoma patients with malignant pleural effusion." (PMID 37775991, 2024). "In lung adenocarcinoma, the prevalence of EGFR mutations varies widely by geographic distribution." (PMID 38347643, 2024). "We identified ten patients from medical records at Massachusetts General Hospital (MGH) who had surgery between 2004 and 2019 for multiple early stage, spatially distinct, lung adenocarcinomas, with at least one specimen positive for the EGFR mutation by routine clinical genotyping (patients 1–10)." (PMID 39406916, 2024). "Their results indicated that imaging omics characteristics based on multiple combined MRI sequences (enhanced T1WI, FLAIR, and DWI) could serve as a non-invasive auxiliary tool for predicting EGFR mutation status in lung adenocarcinoma." (PMID 38773634, 2024).
lung adenocarcinoma (continued). "The discovery of activating mutations of the epidermal growth factor receptor (EGFR) in patients with lung adenocarcinoma led to the development of a new family of biological agents, called tyrosine kinase inhibitors (TKIs), that have revolutionized the clinical management of LC patients." (PMID 39199653, 2024). "In fact, it has been reported that only 0.4% of lung adenocarcinoma patients with EGFR mutations have IP; thus, there are few situations in real-world clinical practice where we wonder whether EGFR-TKIs should be administered to these populations." (PMID 38730686, 2024). "The aim of this study is to develop deep learning models based on 18F-fluorodeoxyglucose positron emission tomography/computed tomographic (18F-FDG PET/CT) images for predicting individual epidermal growth factor receptor (EGFR) mutation status in lung adenocarcinoma (LUAD)." (PMID 39735601, 2024). "Hypopharyngeal cancer is a disease that is associated with EGFR‐mutated lung adenocarcinoma." (PMID 38783639, 2024). "EGFR mutations are a major prognostic factor in lung adenocarcinoma." (PMID 39358807, 2024). "With the rapid development of epidermal growth factor receptor (EGFR) gene testing of lung adenocarcinoma patients has been routinely carried out, EGFR mutations are also possible for some small samples of non-smoking female lung squamous cell carcinoma patients." (PMID 39800484, 2024). "The EGFR mutation rate in Asian patients with lung adenocarcinoma is even higher, reaching 47.9%." (PMID 38774882, 2024). "The high percentage of patients with lung adenocarcinoma bone metastasis suggests that EGFR mutation may promote metastasis formation." (PMID 38791037, 2024). "We used two datasets for EGFR‐mutated lung adenocarcinoma and hypopharyngeal cancer." (PMID 38783639, 2024). "We used AutoPepVax to design a pan-cancer peptide vaccine targeting epidermal growth factor receptor (EGFR) missense mutations commonly found in lung adenocarcinoma (LUAD), colorectal adenocarcinoma (CRAD), glioblastoma multiforme (GBM), and head and neck squamous cell carcinoma (HNSCC)." (PMID 38675381, 2024). "Some researchers suggest that traditional CT imaging signs could aid in predicting EGFR mutation presence in advanced lung adenocarcinoma." (PMID 38027000, 2023). "All lung adenocarcinoma patients with ever TKI treatment had an EGFR mutation." (PMID 37833769, 2023). "According to the results, the peritumoral region of lung adenocarcinoma may also provide important predictive information about EGFR mutations, with the best predictive performance achieved by combining intratumoral and peritumoral 4 mm radiomic features." (PMID 37749461, 2023). "Anaplastic lymphoma kinase (ALK)-mutated or epidermal growth factor receptor (EGFR)-mutated lung adenocarcinoma patients with brain metastases are primarily treated with systemic molecular therapies instead of upfront brain irradiation, especially when there are few and small lesions in the CNS." (PMID 38370347, 2023). "In this study, the clinical characteristics of patients with advanced lung adenocarcinoma with EGFR 19Del, L858R mutation were retrospectively analyzed, and the efficacy of targeted combined with platinum two-drug chemotherapy was compared with that of targeted therapy alone." (PMID 37390279, 2023). "In a previous case report, a 65‐year‐old woman with brain metastasis from a lung adenocarcinoma with the EGFR G719X and S768I mutations was treated successfully with osimertinib as the first‐line therapy, demonstrating the efficacy of this drug and its control of central nervous system symptom." (PMID 37306192, 2023).